EPCAM (epithelial cell adhesion molecule)
Diseases named in the same sentence as EPCAM in open-access papers (continued):
Sharing a sentence is not in itself a finding about the gene and the disease.
cancer (continued). "The system also enriched cancer stem-like properties, with higher expression of stemness-associated genes (CD24, CD44, CD133, ALDHA1, CXCR4, Sox2, Oct4, Nanog, and KLF4) and expansion of CSC populations expressing (CD44, CD90, CD117, EpCAM, and CK19)." (PMID 41149589, 2025). "EpCAM is a membrane glycoprotein expressed in epithelial tissues and various cancers." (PMID 40791212, 2025). "Then, we measured cancer cell apoptosis via surface Annexin V staining of EpCAM+ malignant cells and cancer cell viability by LDH release and MTT assay in preparations before or after stimulation with proinflammatory cytokines and using different effector (E) to target (T) cell ratios." (PMID 40091029, 2025). "Furthermore, EpCAM is capable of enriching, identifying, and characterizing metastatic cells that spread from primary tumors into the fluids of patients with advanced cancer." (PMID 41357552, 2025). "By evaluating the limitations of EpCAM-mediated capture and the challenges posed by epithelial-to-mesenchymal transition, we aim to provide insights into the development of more comprehensive liquid biopsy approaches for cancer management." (PMID 40076201, 2025). "In contrast to the healthy donor cohort, elevated Z scores for EpCAM protein and EpCAM mRNA were observed in the other cancer cohorts, whereas both the early‐stage and intermediate–advanced‐stage HCC cohorts presented varying degrees of elevation in Z scores across all the markers." (PMID 39556692, 2025). "Interestingly, EpCAM-ReTARG TPRIFNαR149A enhanced cancer cell lysis when PBMCs derived from donor #4 were used, who had a low percentage of TPR CD8pos T cells compared to donor #1." (PMID 40243928, 2025). "The use of multiple conjugates against antigens expressed on differentiated PC cells and PCSC cells, e.g., CD44 and EpCAM, could be an effective method to eradicate the heterogeneous population of residual cancer cells completely." (PMID 39846613, 2025). "Recent mechanistic studies have revealed that the RNA aptamer Ep23 is a high-affinity molecular probe that targets EpCAM, demonstrating dual functionality in both selectively binding to EpCAM-expressing human carcinoma cells and facilitating efficient receptor-mediated endocytosis." (PMID 40528159, 2025). "However, the heterogeneous expression of EpCAM in carcinomas, along with its presence in normal epithelial tissues, raises concerns about potential off-target effects and toxicity." (PMID 39996844, 2025). "EpCAM-ReTARGTPR showed potent in vitro capacity to redirect anti-CMVpp65 CD8pos T cells from CMV-seropositive/HLA-B*07:02pos donors to selectively eliminate various EpCAM-expressing carcinoma cell lines and primary patient-derived cancer cells." (PMID 40243928, 2025). "EpCAM-ReTARGTPR showed potent in vitro capacity to redirect TPR-specific CD8pos T cells derived from CMV-seropositive/HLA-B*07:02pos individuals to eliminate various types of EpCAM-expressing carcinomas." (PMID 40243928, 2025). "Compared to EpCAM-ReTARGTPR, in vitro treatment of EpCAMpos carcinoma cell lines with EpCAM-ReTARGTPRvIL2 for 24 h increased the cytotoxic activity of PBMCs containing low levels of TPR-specific CD8pos T cells by ~15%, whereas EpCAM-ReTARGTPRIFNαR149A induced an increase of ~50%." (PMID 40243928, 2025). "Given that EpCAM influences various stemness-related characteristics, we reasoned that EpCAM might be involved in promoting cancer cell migration and invasion." (PMID 39010070, 2024).
cancer (continued). "EpCAM was once thought to serve solely as a cell surface and adhesion molecule; however, in recent years, additional evidence of its role in proliferation, cancer progression and decreased survival in cancer patients has emerged." (PMID 38607014, 2024). "The selection of EpCAM+ cells as the target in this study provides a relevant and practical model that illustrates the potential of biocytometry in critical areas like cancer diagnostics and single cell research and its capability to handle clinically relevant biomarkers." (PMID 39652549, 2024). "Among EpCAM+ cancer cells, six subclusters were identified from the UMAP." (PMID 38169569, 2024). "Besides its involvement in such signaling pathways, EpCAM has also been shown to be a cancer stem cell (CSC) antigen that promotes tumorigenesis." (PMID 39010070, 2024). "Additionally, the levels of ALDH and CD24−/CD44+/EpCAM+ cancer stem cell-like cell markers increased in breast cancer cells after chemotherapy, which helped cancer cells resist chemotherapy drugs and increase their stemness at the level of cell transcription." (PMID 38540708, 2024). "Finally, hybrid GFP+EpCAM+Vim+ cancer cells increased in mixed cSCCs, which are enriched in epithelial plastic cancer cells." (PMID 39075581, 2024). "In addition, the downregulation of stem cell surface markers (AFP, EpCAM, CD133, CD24, and ALDH1A), Wnt and Notch pathway genes, and drug resistance genes was observed, indicating that the EpCAM-apt-Dox targets and impairs cancer stem like cell properties." (PMID 39192365, 2024). "EpCAM is a type 1 transmembrane glycoprotein that is expressed on embryonic stem cells, hepatic progenitor cells, and healthy epithelial tissues and furthermore is aberrantly overexpressed in many epithelial-derived cancers." (PMID 39513807, 2024). "Moreover, BMP9 enhances the cancer stem cell properties in Huh7 and MT cell lines characterized by EpCAM positive LCSCs." (PMID 39199400, 2024). "In recent years, EpCAM has been a target for immunotherapy, and monoclonal antibodies against it have been approved in Europe for the treatment of malignant ascites in patients with cancer and positive EpCAM expression." (PMID 39107717, 2024). "Immunizations with EVs isolated from permanent human cancer cell lines of different origins yielded many antibodies targeting membrane proteins including established TAAs like EpCAM and Her2/neu, but also against proteins which have hitherto never been described to be exposed on the cell surface." (PMID 39329747, 2024). "Interestingly, we identified a cell subpopulation defined as cancer stem cells with a transcriptomic phenotype similar to ECCs and CA-MSCs (EPCAM, MUC1, PROM121, ALDH1A3)." (PMID 38182756, 2024). "However, in cancer, EpCAM becomes highly and homogenously overexpressed on the entire cell membrane." (PMID 37642704, 2024). "Interestingly, other groups have used anti-EpCAM antibody–drug conjugates (ADCs) to target cancer cells." (PMID 38612911, 2024). "The tumorigenic functions of EpCAM have been widely studied in varieties of cancers." (PMID 39010070, 2024). "They utilized an E. coli system, previously developed by the Etherno team (iGEM HKU Hong Kong, 2018), that is capable of producing two specific DNA nanostructures for targeting an epithelial cell adhesion molecule in liver cancer stem cells and nucleolin on the surface of cancer cells, respectively." (PMID 39351063, 2024). "To further identify molecular markers of epithelial plastic cancer cells, we compared the whole gene expression profile of full epithelial (from mouse WD-SCCs) and EpCAM+ plastic cancer cells (comprising EpCAMhigh and EpCAMlow cancer cells from mouse MD/PD-SCCs)." (PMID 39075581, 2024). "Targeting cancer cells expressing EpCAM with specific aptamers could therefore enable the selective delivery of therapeutic agents." (PMID 39513807, 2024).
cancer (continued). "As expected from the phosphoproteomic analysis, the percentage of pIGF1R+ cancer cells was significantly increased in mixed cSCCs, containing EpCAM+ epithelial plastic cancer cells, whereas this percentage practically disappeared in mesenchymal EpCAMneg cancer cells from mesenchymal cSCCs." (PMID 39075581, 2024). "This action subsequently blocks EpCAM-mediated signaling and induces apoptosis in the cancer cells." (PMID 39010070, 2024). "Thus, it is evident that the role of EpCAM in cancer biology extends beyond its initial characterization as a CAM to encompass crucial functions as a CSC marker." (PMID 38612911, 2024). "Catumaxomab has been approved for treating malignant ascites in patients with EpCAM+ cancer." (PMID 38627681, 2024). "Indeed, EpCAM+ITGAV− cancer cells gave rise to cSCCs similar to WD-SCCs, containing mostly EpCAMhigh cancer cells." (PMID 39075581, 2024). "Likewise, EpCAM+ITGAV+ cancer cells expressed higher levels of the plasticity genes Axl, Tnc, Itgb3, and Vcam1 than EpCAM+ITGAV− cancer cells, indicating that EpCAM+ITGAV+ cancer cells exhibit a hybrid E/M phenotype." (PMID 39075581, 2024). "Low expression of EpCAM can reduce the possibility of cancer cell progression." (PMID 38187284, 2024). "The EpCAM aptamer can be used to target these cancer cells with higher specificity." (PMID 38919334, 2024). "Therefore, the major involvement of EpCAM in various types of cancers (including CRC) is likely to involve the functions of EpICD in regulating critical cellular processes such as EMT, CSC signaling and metastasis." (PMID 39010070, 2024). "In contrast, most of the ITGAV+ cancer cells in mixed cSCCs retained EpCAM expression." (PMID 39075581, 2024). "The expression of CD45 in CRC can be induced after chemotherapy in the EpCAM + cancer stem-like cells (CSCs), which collectively enhances stemness and may contribute to chemoresistance." (PMID 38612832, 2024). "We observed that WD-SCCs were formed of epithelial α6-integrin+EpCAM+ cancer cells, MD/PD-SCCs contained a mixture of epithelial α6-integrin+EpCAM+ and mesenchymal α6-integrin+EpCAM− cancer cells, and PD/S-SCCs contained only mesenchymal α6-integrin+EpCAM− cancer cells." (PMID 38914547, 2024). "Interestingly, anti-PD-L1 therapy favored the elimination of epithelial EpCAM+ cancer cells and increased the frequency of mesenchymal EpCAM− cancer cells." (PMID 38914547, 2024). "However, EMT during cancer metastasis can decrease EpCAM expression and can vary depending on the cancer type." (PMID 39492906, 2024). "Although great progress has been made in the past few decades, the context-specific expression profile of EpCAM and its regulation urgent need to be urgently determined for the application of EpCAM-based techniques in both basic and translational cancer research." (PMID 38791091, 2024). "ITGAV expression was mainly observed in EpCAM− cancer cells in mesenchymal cSCCs." (PMID 39075581, 2024). "Although numerous anti-EpCAM mAbs have been developed and tested in clinical studies, many early candidates, such as adecatumumab and edrecolomab, showed limited clinical benefit and raised safety concerns for cancer patients." (PMID 39595576, 2024). "Also, EpCAM is subjected to regulated proteolytic cleavage and the majority of antibodies that recognize EpCAM on cancer cells target the terminal (signal peptide) part of the extracellular domain that can be cleaved off." (PMID 38928484, 2024). "In addition, a cluster of genes associated with epithelial and cancer cells (for example, CDH1, EPCAM, BIRC5 and CD276) was significantly downregulated in resected tumors with nivolumab/relatlimab-induced MPR." (PMID 38689060, 2024). "Since the age of cancer onset in biallelic EPCAM deletion carriers is extremely early, GI surveillance may be recommended at even younger age as for CMMRD patients harboring germline mutations in other MMR genes." (PMID 38467830, 2024).
cancer (continued). "Additionally, we explicated the role of BMP9 in advocating cancer stem cell properties, as indicated by Epithelial Cellular Adhesion Molecule (EpCAM) positivity." (PMID 38256056, 2024). "Cancer cells from WD-SCCs showed a high level of EpCAM expression and were designated full epithelial cancer cells, whereas epithelial EpCAM+ cancer cells from MD/PD-SCCs exhibited variable EpCAM expression and were classified as EpCAMhigh or EpCAMlow." (PMID 39075581, 2024). "EPCAM is used as a target for immunotherapy in the treatment of various carcinomas." (PMID 39071494, 2024). "EpCAM is a pan-carcinoma antigen that is overexpressed in many carcinomas." (PMID 38833451, 2024). "This technique is limited to cancers that express EpCAM (i.e., carcinomas) and will not detect tumors that have undergone epithelial-mesenchymal transition with loss of EpCAM expression." (PMID 37256537, 2023). "CTC detection methods based on EpCAM+ cell quantification in cancer patients could miss those cells that, in preserving metastatic potential, lose this marker (or simply do not express it)." (PMID 37373781, 2023). "Next, we simulated cell salvage followed by leucodepletion and irradiation of whole blood units from healthy donors, which were inoculated with a known amount of cancer cells expressing the epithelial cell adhesion molecule (EpCAM) (HCT116 and CaCo-2 cell lines)." (PMID 37373781, 2023). "Similarly, catumaxomab, a drug originally approved for treating malignant ascites, targets on EpCAM and CD3 in late-stage GI tumors." (PMID 38455361, 2023). "Likewise, HCC1500 cells have been classified as luminal, due to a predominant population of cells that are positive for EpCAM and CD24 or as basal B, owing to an enrichment for gene clusters associated with cancer stem cell and invasive phenotypes." (PMID 36768838, 2023). "Moreover, the EpCAM overexpression in these patients correlated with enhanced cancer cell proliferation, oncogenic signaling, chemoradiotherapy resistance, and decreased overall survival." (PMID 37509310, 2023). "The therapeutic antibodies targeting EpCAM in combination with HGFR inhibitors may hold great potential for cancer patients with high EpCAM expression." (PMID 37543570, 2023). "However, although in vitro experiments have shown significant anticancer effects, clinical trials of adecatumumab, huKS-IL-2, and catumaxomab targeting EpCAM exhibited limited clinical benefits for cancer patients." (PMID 37853413, 2023). "The EpCAM is considered as a multi-functional transmembrane protein associated with the regulation of cell adhesion, proliferation, migration, stemness, and EMT of cancer cells." (PMID 37853413, 2023). "Altogether, these data implied that BAP31 regulates the N-glycosylation of EpCAM and may represent a potential therapeutic target for cancer therapy." (PMID 37834237, 2023). "Another common cancer marker is Epithelial Cell Adhesion Molecule (EpCAM)." (PMID 36875773, 2023). "Moreover, certain specific subpopulations of CTCs (e.g., EpCAM− CTCs or CTC clusters) have been shown to play a critical role in cancer metastasis and the development of therapy resistance." (PMID 38001632, 2023). "The prognostic relevance of EpCAM expression has also been demonstrated in various types of cancer." (PMID 37627911, 2023).
cancer (continued). "In order to evaluate that only the simultaneous targeting in the presence of anti-CEA and anti-EpCAM RevTMs triggers a full activation and cytotoxic potential of the Dual-RevCAR T-cells upon their encounter with CEA+ EpCAM+ cancer cells, cytotoxic assays were performed." (PMID 38169746, 2023). "Therefore, in this work, we developed a facile conductive nanofibers-enhanced microfluidic device for efficient separation and rapid release of EpCAM-positive cancer cells." (PMID 37232858, 2023). "In addition, we developed novel RevTMs for an adaptor AND-gate combinatorial targeting approach, with the potential to further improve the specific recognition of CEA+ EpCAM+ cancer cells." (PMID 38169746, 2023). "Finally, the epithelial cell adhesion molecule (EpCAM) is a structural MP that plays various roles in physiological processes and diseases such as cancer and is known to be overexpressed in cancerous cells." (PMID 37175137, 2023). "Therefore, this study reported that circulating cancer stem cells from patients with cancer (tumospheres positive for EpCAM and CD 44 +, and CD24− or CD24 low and positive ALDH1 activity) can be implanted in the CAM to generate tumors." (PMID 37834193, 2023). "In addition, physiological levels of BMP9 (2‐5 ng/mL) promote EpCAM+ cancer stem cell (CSC) properties in Huh7 cells, but high levels (200 ng/mL) inhibit CD44+ CSC properties in Hep3B cells." (PMID 37132170, 2023). "The role of the epithelial cell adhesion molecule (EpCAM) in cancer is still unclear." (PMID 37154925, 2023). "In order to elucidate the functional impact of SF3B1K700E on the transcriptome, we isolated cancer cells of mouse tumors by fluorescence-activated cell sorting (FACS) of Epithelial cell adhesion molecule (EpCAM) positive cells and performed RNA-sequencing (RNA-seq)." (PMID 37823551, 2023). "Furthermore, we have compared their EpCAM expression to that of several often used cancer cell lines." (PMID 37055551, 2023). "EpCAM is considered a “universal” epithelial marker for various cancer types." (PMID 37998325, 2023). "In light of the cytosolic localization of EpCAM and the altered phenotype in H-Ras-EpCAM-L240A cells, we hypothesized that EMT transcription factors together with other cancer-associated factors may be playing an important role." (PMID 37192201, 2023). "Furthermore, we investigated the CD44 status in EpCam+ /CD45− CRC in the cancer patient cohorts following the idea of detecting cancer stem cells." (PMID 36100762, 2023). "Interestingly, cells of so-called cHCC-CCA with stem cell features of intermediate type frequently express EpCAM, whereas cells in typical subtype and cholangiocellular subtype cancers only show focal staining." (PMID 36672443, 2023). "In CRC, EpCAM is overexpressed in over 90% of all cancer cells." (PMID 37175871, 2023). "EpCAM interacts with multiple signaling pathways, which can affect cancer growth and progression." (PMID 37192201, 2023). "We assessed that the cancer cells in 23 of 26 samples are highly EpCAM‐positive, with more than 50% cancer cells expressing this epithelial marker (average from all samples = 80.4%; 95% CI = 0.003) and exhibiting more epithelial phenotype based on their positive MET score." (PMID 36550781, 2023). "Although EpCAM is universally expressed by CTCs, the expression may change after cancer progression or during cancer treatment." (PMID 37109080, 2023). "Inhibiting EpCAM glycosylation is expected to have an inhibitory effect on cancer." (PMID 37834237, 2023). "Thus, the majority of mAbs that recognize EpCAM on cancer cells bind specifically to the EpCL domain (amino acids 24–80) of EpCAM, and that region is considered to offer high immunogenicity." (PMID 36918661, 2023).